IRF3 (interferon regulatory factor 3)
Diseases named in the same sentence as IRF3 in open-access papers (continued):
Sharing a sentence is not in itself a finding about the gene and the disease.
viral infection (continued). "The results presented in this paper bring new data describing the IRF-3-mediated modulation of VACV–host interactions that could be useful in the design of other virus-based vaccines or in the treatment of different viral infections." (PMID 34696416, 2021). "One such host gene normally induced upon viral infection is interferon regulatory factor 3 (IRF-3)." (PMID 33996913, 2021). "Moreover, the VP35 protein of Ebola virus (EBOV) interacts with IKKε and TBK1 during the early phase of viral infection; this physical interaction with IKKε further prevents the interaction of IKKε with IRF3, IRF7, and MAVS214." (PMID 34782737, 2021). "In addition to inducing antiviral genes, IRF3 also mediates innate immunity against virus infection by activating an antiviral, pro-apoptotic pathway." (PMID 33805458, 2021). "Therefore, LINC02605 is an induced lncRNA by viral infection and plays a positive feedback in antiviral immune response through modulating the nuclear translocation of IRF3." (PMID 34804040, 2021). "Among the USP members, USP1 functions as a viral infection-induced physiological enhancer of TBK1 expression when bound to USP1 the K48-linked polyubiquitination of TBK1, resulting in enhanced TLR3/4 and RIG-I-induced IRF3 activation and IFNβ secretion." (PMID 34707613, 2021). "IRF3 is a critical mediator of type I interferons response following viral infection." (PMID 33411856, 2021). "Thus, NLRX1 helps to maintain IRF1 upregulation, while inhibits IRF3 dimerization upon viral infection." (PMID 33525671, 2021). "These indicate that JMJD6 catches RNF5 to degrades IRF3 in the nucleus upon viral infection." (PMID 33684176, 2021). "The increased IRF3a/IRF3 after viral infection may be a mechanism employed by virus to weaken the IFN response." (PMID 34868032, 2021). "IRF3 plays a significant role in host survival following viral infection." (PMID 33411856, 2021). "Interferon regulatory factor 3 (IRF3) has been known as a transcription regulator of many cellular responses in many cell types that is known to be critical for innate immunity against viral infection." (PMID 34464509, 2021). "Studies in Irf3−/− mice have demonstrated the absence of IRF3 imparts a high degree of susceptibility to a wide range of viral infections." (PMID 33805458, 2021). "Here, we show that SARS-CoV-2 can block IRF3 and NF-κB activation early during virus infection." (PMID 34166398, 2021). "IRF3 plays an extremely pivotal role in the induction of IFN in responding to viral infection." (PMID 34745071, 2021). "It recognizes dsRNA associated with a viral infection, and induces the activation of IRF3, unlike all other toll-like receptors which activate NF-κB (Kannakiet al., 2010)." (PMID 34970593, 2021). "Nevertheless, IRF3 and the predicted miRNA interactions do illustrate that there might be complex and dynamic host-cell miRNA fine-tuning mechanisms acting during viral infections." (PMID 33013890, 2020). "Therefore, we demonstrate that the RIPA branch of IRF3 can be targeted therapeutically to prevent virus infection." (PMID 32295140, 2020). "A serine-rich cluster is present in the duck sequence near Serine 496 and contains the motif HLGLS, which resembles the consensus pLxIS motif containing (human) Serine 442 that becomes phosphorylated by IKKβ and TBK1 upon viral infection, leading to recruitment and phosphorylation of IRF3." (PMID 32272772, 2020). "Finally, to keep IRF3 in the nucleus, DNA-PK is activated in response to virus infection and phosphorylates IRF3 at T135." (PMID 32645843, 2020). "Additionally, viral infection promotes the nuclear localisation of the E3 ubiquitin ligase TRIM26, allowing TRIM26 to bind phosphorylated IRF3 in the nucleus and promote its K48-linked ubiquitination and degradation." (PMID 32645843, 2020). "The absence of antiviral genes in IRF3 deficiency leads to susceptibility to a wide range of viral infections." (PMID 32295140, 2020).
viral infection (continued). "Since mimicking IRF3 activation forfeited inhibitory effect of IRF3 on Wnt signaling and cell proliferation, we speculated that virus infection, which activates IRF3, may activate Wnt signaling." (PMID 33188184, 2020). "After virus infection, a fraction of the ESCRT-II subunit ELL-associated protein of 30 kDa (EAP30, also known as SFN8) localises to the nucleus where it interacts with activated IRF3 and CBP and promotes binding of the holocomplex to target gene promoters." (PMID 32645843, 2020). "Here, the Ser 396 is essential for IRF3 activation, especially after viral infection." (PMID 33391252, 2020). "TBK1 and IRF3 are the key effectors during viral infections to induce IFN production." (PMID 32486349, 2020). "The interaction between PPRV N protein and cellular IRF3 in the context of viral infection was investigated by performing an immunoprecipitation experiment, which showed conclusively that IRF3 immunoprecipitated N protein in PPRV-infected HEK-293T cells and in goat primary macrophages." (PMID 31167907, 2019). "Since ZAP expression is induced by viral infection via an IRF-3-dependent pathway, the HTLV-1 burst might trigger ZAP expression." (PMID 31842935, 2019). "Considering that PINK1 binds IRF3 after viral infection in macrophages, we speculate that YAP1 might be involved in the PINK1-mediated antiviral innate immune response." (PMID 31139191, 2019). "Upon virus infection, IRF3 is phosphorylated by the kinases TBK1 and IKKε at its C-terminus, forming dimers that are then transported into the nucleus, subsequently forming a complex with the coactivators of the p300/CBP family and initiating transcription of target genes, including IFN-β." (PMID 31340999, 2019). "After viral infection, pattern recognition receptors detect viral molecular features and activate the essential transcriptional regulator IRF3 via phosphorylation of its C-terminal trans-activation domain by TBK1/IKKε, and trigger the production of type I IFNs." (PMID 31618847, 2019). "IRF3 interacts with other transcription factors, coactivators and repressors including other IRFs and NF-κB and thereby regulates T cell differentiation into Th1, Th2 and Th17 cells as well as induces apoptosis during viral infections." (PMID 30939763, 2019). "In addition, PINK1 interacts with Yes-associated protein 1 (YAP1) upon viral infection and impairs YAP1/IRF3 complex formation." (PMID 31139191, 2019). "Viral infection triggers host innate immune responses through activation of the transcription factors nuclear factor κB (NF-κB) and interferon regulatory factor 3 (IRF3), which coordinately regulate the expression of type I interferons such as interferon-β (IFN-β)." (PMID 31905881, 2019). "In the present study, we demonstrated that metabolite-sensing TGR5 could be regarded as an ISG in viral infection which inhibited viral propagation by promoting IFN-I production via AKT-mediated IRF3 activation." (PMID 30333836, 2018). "For example, IRF3 forms a complex with CREB binding protein (CBP)/p300 histone acetyltransferase (HAT) through the IAD1 domain for the induction of Ifnb1 transcription in response to virus infection." (PMID 30671058, 2018). "IRF-3 activation regulates the expression of interferons in response to viral infection." (PMID 30274155, 2018). "Much like other DExD/H box RNA helicases, SNRNP200 requires a functional ATPase/helicase activity in addition to a competent Sec63-1 domain of unknown function to promote IRF3-dependent IFN induction upon virus infection." (PMID 29854853, 2018). "In addition, the arenavirus NP counteracts the host type I interferon (IFN-I) response during viral infection by preventing the activation and nuclear translocation of interferon regulatory factor 3 (IRF-3), and subsequent induction of IFN-I production." (PMID 30001425, 2018). "Further knockdown of IRF3 or IRF7 enhanced M1 virus infection in HCT-116 cells." (PMID 29670091, 2018).
viral infection (continued). "TBK1 was initially identified in the context of its ability to regulate NF-κB in vitro, yet later studies in TBK1 deficient mice demonstrated that TBK1 is an essential component of the IRF3 signaling pathway after both viral infection and stimulation of TLR3 by dsRNA31." (PMID 29343779, 2018). "IRF3 could be detected in Brd3 immunoprecipitates and the interaction was increased after virus infection." (PMID 28045112, 2017). "It will be interesting to determine in future studies whether EAP30 undergoes post-translational modifications and/or conformational changes after viral infection that alters its ability to interact with IRF3 and CBP." (PMID 29084253, 2017). "Furthermore, we found that viral infection induced TBK1-dependent ERRα stabilization, which in turn associated with TBK1 and IRF3 to impede the formation of TBK1-IRF3, IRF3 phosphorylation, IRF3 dimerization, and the DNA binding affinity of IRF3." (PMID 28591144, 2017). "Thus, IRF3 is essential for the induction of IFN-β as an early response to virus infection and IRF7 leads to the amplification signals of IFN-α genes." (PMID 29053748, 2017). "A report has demonstrated that a viral infection-induced E3 ligase AMFR/gp78 interacts with STING constitutively and mediates K27-linked ubiquitination of STING, which is critical for STING-mediated recruitment of TBK1 and IRF3 after DNA virus infection." (PMID 28534493, 2017). "Upon viral infection, TRIM14 undergoes Lys-63-linked polyubiquitination at lys-365 and recruits NF-κB essential modulator to the MAVS signalosome, leading to the activation of both IRF3 and NF-κB pathways." (PMID 28211536, 2017). "Viral infection that activates IRF3 relieves the inhibition of YAP." (PMID 31225446, 2017). "Importantly, knocking down of A20 expression results in enhanced IRF-3-dependent transcription triggered by the stimulation of TLR3 or virus infection." (PMID 27023883, 2016). "Upon viral infection, IRF3 is phosphorylated and activated by active TBK1 or IKKε." (PMID 26811330, 2016). "Our findings address the direct regulation of RIG-I by IRF-3 upon viral infection." (PMID 27662626, 2016). "In addition, IKKγ is required to activate interferon regulatory factor 3 (IRF3) in response to viral infection." (PMID 27992555, 2016). "The activation of IRF3 after virus infection was comparable in control and PML-knockdown HF cells." (PMID 25812002, 2015). "Interestingly, an alternative splice form of the related protein IKKε that is truncated in a similar location encodes a dominant negative signaling molecule that inhibits viral infection-induced activation of IRF3 and NFκB." (PMID 25658809, 2015). "IRF3 is essential for the immediate induction of transcription factors after virus infection." (PMID 25710018, 2015). "TRIM26 bound to and induced IRF3 polyubiquitination in nucleus after virus infection." (PMID 25763818, 2015). "The IFN response in T2DM was also indicated by the significant geneset: GRANDVAUX_IRF3_UP, containing genes up-regulated in Jurkat T cells by expression of a constitutively active form of IRF3, which is normally activated during viral infections and induces type I IFNs." (PMID 25956355, 2015). "Sodium arsenate is also an inducer of the cell stress pathway and we chose this chemical to look at the role of Npro in inhibition of apoptosis, both because mitochondria play a central role in IRF3 signalling and because virus infection activates the cell stress pathway." (PMID 24551175, 2014). "IRF3 is the key regulator of type I IFN gene expression elicited by viral infection." (PMID 24722640, 2014). "IRF-3 is an important mediator for IFN induction in response to viral infection." (PMID 24727952, 2014). "Recent work has linked the central role played by IRF3 in signaling both interferon production and apoptosis, however little is known about the IRF3 signaling pathways targeted by Npro to inhibit the apoptotic pathway, important in generating persistent viral infections." (PMID 24551175, 2014).
viral infection (continued). "The NF-κB and IRF3 signaling pathways are known to be cross-coupled through multiple positive and negative interactions, whose precise temporal interaction is critical for determining the cellular outcome of viral infection." (PMID 24710104, 2014). "It has been shown that apoptosis may be induced during viral infection by IRF3-mediated activation of Bax." (PMID 24551175, 2014). "Importantly, PMLIV is also able to enhance IRF3 phosphorylation resulting in a dramatic IFN-β production in response to viral infection, thus protecting yet uninfected cells." (PMID 24586174, 2014). "Indeed, TRIM21 was shown to interact directly with IRF3 upon viral infection and to interfere with its interaction with Pin1." (PMID 24586174, 2014). "In CSFV-infected cells, virus infection robustly induced IRF3 nuclear translocation." (PMID 24034559, 2013). "Although the transcription factors IRF-3 and IRF-7 are considered master regulators of type I interferon (IFN) induction and IFN stimulated gene (ISG) expression, Irf3−/−×Irf7−/− double knockout (DKO) myeloid dendritic cells (mDC) produce relatively normal levels of IFN-β after viral infection." (PMID 23300459, 2013). "However, IRF-3a with an intact IAD domain has been shown to form a heterodimer with IRF-3 following viral infection and inhibit IRF-3 transcriptional activity." (PMID 23658645, 2013). "We reasoned that this might reflect a low level of IRF3 activation during virus infection, which might be difficult to discern by immunofluorescence staining." (PMID 22629479, 2012). "Regulation of these genes is complex, with different cell types and different tissues activating distinct genes through IRF-3 and it is clear that the method of stimulation of IRF-3 following viral infection can lead to different programs of downstream gene expression." (PMID 22911267, 2012). "By 6 hr post infection, both Ku80 and DNA-PKcs had accumulated in these viral factories together with the IRF-3-activating kinase TBK1, consistent with its role in this sensing pathway, although IRF-3 was mostly nuclear, reflecting its activation by virus infection." (PMID 23251783, 2012). "Therefore, like other members of its family, VZV is able to interfere with the activation of IRF3 following viral infection." (PMID 21347389, 2011). "We conclude that the transcription factor IRF3 is targeted for turnover and inactivation through distinct mechanisms from both the host cells and virus, leading to the inhibition of IFNβ gene expression during acute and persistent viral infections." (PMID 21677781, 2011). "Thus, the degradation of IRF3 during virus infection is likely to play a key role in the turn-off of IFNβ expression." (PMID 21677781, 2011). "Due to deficient RIG-I gene function in Huh 7.5 cells, virus infection will not lead to IRF-3 activation and IFN secretion." (PMID 21936899, 2011). "In addition to NF-κB and AP-1, the interferon regulatory factor (IRF-3) pathway controls a distinct, but interrelated, arm of the inflammatory response to viral infection." (PMID 19592477, 2011). "During viral infection, IRF3 and NF-κB co-operate to activate the IFN-β and the CCL5 promoters." (PMID 21931555, 2011). "Virus infection induces IRF3 protein phosphorylation, homodimerization and nuclear translocation." (PMID 21677781, 2011). "Indeed, the main experiments demonstrating that ORF47p interferes with the activation of IRF3 were performed in the context of viral infection using WT VZV, vaccine ROka and mutant strains." (PMID 21347389, 2011). "IFIT1 is commonly associated with IRF3 signaling in response to IFN treatment and viral infection." (PMID 21999375, 2011). "Induced IRF3 degradation was previously observed with other virus infections." (PMID 21677781, 2011).
viral infection (continued). "Taken together, these results demonstrate that NOX2 contributes to the regulation of SeV-induced IFNβ- and ISG56-promoter activities, thereby suggesting that NOX2 is an essential component of the signaling pathway triggering IRF-3 activation following virus infection." (PMID 20532218, 2010). "IRF3 is a transcription factor controlling interferon responses to viral infection." (PMID 20886104, 2010). "As ATF2 and c-Jun are activated in response to a wide variety of stress-related stimuli that occur following virus infection, assembly of the enhanceosome is largely dependent on NF-κB and IRF3/7, and therefore, the catalytic activity of the IKK and IKK-related kinases." (PMID 21994600, 2010). "The RLRs also activate NFκB and IRF3 following viral infection and poly(I:C) stimulation." (PMID 19452017, 2009). "We hypothesize that this increased IFN production is secondary to the significantly increased viral infection in IRF-3−/− cells." (PMID 17676997, 2007). "Finally, IRF-3 also appears to regulate the basal expression of specific sensors of viral infection, which in turn affects the antiviral state of a cell prior to virus entry." (PMID 17676997, 2007). "It has already been implicated in host response to viral infections, as it was shown that IFI44 silencing inhibits the replication of multiple viruses, whereas its overexpression inhibits the antiviral response due to negative regulation of the interferon pathway mediated by IRF-3 and NF-κB." (PMID 39859996, 2025). "We also tested whether MAVS and IRF3 localize to SGs in response to viral infection." (PMID 38295168, 2024). "However, the function of IRF3/7 upon virus infection in chickens is still limited." (PMID 39872942, 2024). "Mutations affecting IRF family members IRF1, IRF3, IRF7, IRF8, or IRF9 have been described in patients presenting with inborn errors of immunity (IEI) highlighting the importance of these factors for the cellular host defense against mycobacterial and/or viral infections." (PMID 37809068, 2023). "Upon viral infection, macrophages reduce the expression of 7-dehydrocholesterol reductase (DHCR7, an enzyme that catalyzes 7-dehydrocholesterol [7-DHC] to cholesterol), which causes the accumulation of 7-DHC in macrophages to enhance IRF3-dependent antiviral immunity." (PMID 36750575, 2023). "Similarly, for IRF3 phosphorylation, both the viral infection with Cyclo (Phe-Pro) and the 6.25 μg/mL naringenin group with Cyclo (Phe-Pro) added to the viral infection significantly elevated the phosphorylation level of IRF3 compared with the viral infection group." (PMID 38005850, 2023). "Notably, SETX and IRF3-dependent signaling are also interconnected during virus infection." (PMID 37147318, 2023). "Additionally, this is not the first example of a Irf3 spontaneous variant identified in mice modulating susceptibility to bacterial or viral infections." (PMID 37733807, 2023). "Previous studies reported that viral infection could induce the phosphorylation and dimerization of interferon regulatory factor 3 (IRF3), an important transcription factor in innate antiviral immunity, followed by triggering of the transcription and expression of type I IFNs." (PMID 35573779, 2022). "To determine whether HO-1 is involved in the regulation of IRF3 activation by p21 after IAV infection, we transfected the HO-1 expression plasmid into p21-KO HEK293T cells and assessed the activation level of IRF3 at different time points after virus infection." (PMID 35180274, 2022). "IRF3 activation could lead to type I IFN production in cells respond to viral infection." (PMID 36743911, 2022). "Interestingly, viral infection activates non-transcriptional IRF3–Bax interactions and causes MOMP and cell death." (PMID 34359890, 2021).